CD93 (CD93 molecule)
Diseases named in the same sentence as CD93 in open-access papers (continued):
Sharing a sentence is not in itself a finding about the gene and the disease.
tumor (continued). "We used integrated bioinformatics approaches to show that the expression of CD93 was closely related to the tumor stage and immune infiltration of pan-cancer and affected the prognosis of patients, so it has potential value to be a biomarker of prognosis." (PMID 35265666, 2021). "The results of GSEA showed that, in COAD, BLCA, KIRC, and LIHC, the gene set of the CD93 high expression group was mainly enriched in the cell migration and tissue migration pathway, which is closely related to tumor angiogenesis." (PMID 35265666, 2021). "CD93, a novel biomarker expressed on vascular endothelial cells, is essential for tumor angiogenesis." (PMID 35265666, 2021). "We further examined if the decreased tumoral B cell infiltrate was attributable to a specific B cell subset and found that PKD inhibition primarily decreased the frequency of follicular (CD19+CD93-CD21LoIgDHi) B cells within the tumor." (PMID 35046933, 2021). "Recently, it has been reported that CD93 is a new type of angiogenic activator, mainly by promoting endothelial cell adhesion and accelerating tumor angiogenesis, thus affecting tumor growth." (PMID 35265666, 2021). "Previous studies indicated that an increased expression of CD93 can promote vascular endothelial cell migration and vascular maturation in tumor tissue, also leading to T-cell depletion." (PMID 35265666, 2021). "The transmembrane receptor, CD93, is highly expressed in tumour vessels of multiple cancers, indicating that CD93 functions by organizing the extracellular matrix and mediating vascular maturation." (PMID 32626543, 2020). "Each family member has strong links to tumour development and in particular CD93, CLEC14A and CD248 have been proposed as attractive candidate targets for cancer therapy." (PMID 31287944, 2019). "On one hand, they up-regulate collagens which bind to either CD93 and/or integrin receptors on tumour cells to positively induce tumour growth." (PMID 31672982, 2019). "Thrombomodulin, CD93 and CLEC14A can be expressed by endothelial cells, whereas CD248 is expressed by vasculature associated pericytes, activated fibroblasts and tumour cells among other cell types." (PMID 31287944, 2019). "We found that CD93 colocalized with α5β1 integrins in endothelial filopodia and identified CD93 as a novel regulator of β1 integrin activation during tumor angiogenesis." (PMID 29763414, 2018). "Above all, we have uncovered a novel CD93/MMRN2/β1 integrin/fibronectin signaling axis that orchestrates tumor angiogenesis and vascular stability in cancer." (PMID 29763414, 2018). "Here, we demonstrate that CD93 regulates β1 integrin signaling and organization of fibronectin fibrillogenesis during tumor vascularization." (PMID 29763414, 2018). "Eighty-nine out of the 101 patients had a significantly (P < 0.001) higher expression of CD93 in tumour tissue compared to matched normal tissue." (PMID 26008729, 2015). "Quantification of total CD93 in the tissue lysates, using ELISA, showed a significantly 82 % higher expression in tumour tissues (mean, 7.1; standard deviation (SD), 3.33 ng/mg) compared to matched normal tissues (mean, 3.9; SD, 2.04 ng/mg) (P < 0.001)." (PMID 26008729, 2015). "This CD93-IGFBP7 interaction leads to aberrant tumor vascularity." (PMID 40943530, 2025). "This suggests that CD93 may play an immunosuppressive role in the tumor microenvironment, and that targeting the CD93-related signaling pathway may represent a novel therapeutic strategy for tumor immunotherapy." (PMID 40943530, 2025). "Therefore, CD93 has emerged as a novel angiogenesis activator, primarily enhancing endothelial cell adhesion and expediting tumor angiogenesis." (PMID 40943530, 2025). "How does CD93 exert its immunosuppressive effects within the tumor microenvironment?" (PMID 40943530, 2025).
tumor (continued). "This approach not only facilitates chemotherapy drug delivery, enhances the anti-tumor response to gemcitabine or fluorouracil, and significantly increases intratumoral effector T cells when the CD93 pathway is inhibited, rendering mouse tumors more responsive to immune checkpoint treatment." (PMID 40943530, 2025). "Its upregulation in a plethora of solid organ tumors, and promising anti-tumor effects when disrupted, especially given its distinct vascular normalization effects, give credence to further investigation into how CD93 acts as an intercellular adhesion molecule and promoter of EC formation." (PMID 38468017, 2024). "Notably, CD93–/– endothelial cells facilitated tumor cell transmigration across the endothelial monolayer, resulting in a significant increase in tumor cells penetrating the endothelial barrier." (PMID 38441970, 2024). "Moreover, much like CD93, CD248, TM, and CLEC14a, selectins and select galectins have been implicated in tumor angiogenesis and metastasis, the mechanisms of which expand the possibilities of study for the CTLDs at hand." (PMID 38468017, 2024). "CD93 has been shown to facilitate tumor progression by promoting angiogenesis." (PMID 38250037, 2024). "Blockade of CD93 normalizes tumor vasculature, thereby benefiting tumor therapy." (PMID 38250037, 2024). "In tumor-bearing mice, we found that the Cd93 mRNA level was notably upregulated in pMCs." (PMID 38250037, 2024). "Interestingly, the relative area of the vasculature covered by desmin-positive pericytes was significantly reduced in CD93–/– HCmel12 tumor vessels as compared with wild-type tumor vessels." (PMID 38441970, 2024). "We next assessed whether the improved tumor endothelial barrier function observed in response to VEGRF2 inhibition in CD93–/– mice would reduce the metastatic spread." (PMID 38441970, 2024). "Blocking CD93 normalized tumor vasculature and promoted lung tumor infiltration of DCs." (PMID 38250037, 2024). "Further, in subcutaneous fibrosarcoma model, CD93 KO mice had reduced tumor size." (PMID 38468017, 2024). "The IGFBP7 receptor CD93 has been identified as one of the top 20 genes in tumor angiogenesis." (PMID 39045455, 2024). "Consequently, STAD patients with tumor grade three (T3) exhibited significantly higher expression of CD93 than did normal tissue and other groups." (PMID 39190192, 2024). "Sun and his team discovered that, after inhibiting CD93, the tumor vasculature could be normalized, by enhancing blood flow, and increasing tumor hypoxia, moreover, the anti-tumor response to gemcitabine or fluorouracil was also strengthened." (PMID 38955924, 2024). "Similarly, the levels of the tight junction molecules claudin-5 and zonula occludens-1 (ZO1) were also significantly decreased in CD93–/– tumor vessels as compared with the wild-type group." (PMID 38441970, 2024). "Except for platelets showing the highest Cd93 mRNA expression, Cd93 mRNA level in p-pMCs was comparable to that in ECs, bone marrow cells and MLE-12 mouse alveolar epithelial cells, even in tumor ECs reported to overexpress CD93, whereas Ccl21a mRNA was most highly expressed in p-pMCs." (PMID 38250037, 2024). "However, the effects of CD93 blockade on orthotopic tumors, known to display tumor microenvironments more similar to human cancers, is a subject of ongoing investigation." (PMID 38468017, 2024). "The contrast between CD93 blockade with our mAb leading to tumor vessel normalization compared to companion investigations of group XIV protein KO leading to increased MVD and dysfunctional vessels within tumors in the absence of their CTLD protein, is pronounced." (PMID 38468017, 2024). "In contrast, it was also demonstrated that the IGFBP7-CD93 axis was related to disordered tumor vasculature and that CD93 neutralizing antibody could normalize tumor vasculature." (PMID 39045455, 2024).
tumor (continued). "Next, we addressed whether the pronounced destabilization of the tumor vasculature and the increased metastasis formation observed in CD93–/– mice was dependent on the hyperactivation of VEGFR2." (PMID 38441970, 2024). "CD93 expression and upregulation on tumor endothelium has also been confirmed with immunostaining." (PMID 38468017, 2024). "CD93 is a member of the C-type lectin transmembrane protein family and is expressed on the membrane of multiple cell lineages, especially endothelial cells of tumor vessels." (PMID 39190192, 2024). "Therefore, lungs from CD93–/– and wild-type mice bearing HCmel12 tumors were examined for the presence of metastases 24 days after tumor implantation." (PMID 38441970, 2024). "Zhang and colleagues found that an increased expression of CD93 was associated with a poor prognosis in cancer patients and was correlated with mismatch repair (MMR) gene expression, tumor mutation burden (TMB), microsatellite instability (MSI) and immune cell infiltration." (PMID 37443812, 2023). "In addition, since CD93 is highly expressed in vascular networks within solid tumors, it can favor tumor vascularization and growth." (PMID 37443812, 2023). "Hindering the CD93-IGFBP7 axis by CD93 or IGFBP7 mAb could normalize tumor vasculature to suppress tumor growth." (PMID 37483608, 2023). "Dystroglycan (DG), a laminin-binding protein that could be upregulated in tumor vascular ECs, played a critical role in angiogenesis and had close interactions with CD93." (PMID 37660019, 2023). "In conclusion, CD93 was a promising target for normalizing the tumor vasculature." (PMID 37660019, 2023). "Our findings further demonstrated that CD93 was closely correlated with angiogenesis in LIHC, as among the most frequently altered genes closely associated with CD93 are many genes associated with tumor vascularization." (PMID 37483608, 2023). "Looking at the data discussed in this section, we can speculate that CD93 may have an immunosuppressive role in tumor environments since it can limit immune cell infiltration, favoring the immune-escape of tumor cells." (PMID 37443812, 2023). "However, it has been shown that combining immunotherapy with CD93-blocking agents can sensitize tumors to immune-checkpoint blocker therapy, improving therapy response in preclinical tumor models." (PMID 37443812, 2023). "The density of CD93+ cells in tumor regions was higher than in stomach regions (p = 0.0220)." (PMID 36761750, 2023). "CD93 had been identified as one of the top 20 genes in tumor angiogenesis." (PMID 37660019, 2023). "The positive rate of CD93+ cells in tumor regions was higher than in stomach regions (p = 0.0110)." (PMID 36761750, 2023). "By ELISA, IHC, western blot, gene expression analysis, and real-time PCR, they found that CD93 expression is upregulated in tumour tissue compared to normal tissue, while soluble CD93 in plasma from cancer patients is downregulated compared to plasma from healthy patients." (PMID 37660019, 2023). "Moreover, the use of monoclonal antibodies able to block CD93/IGFBP7 interaction in mouse tumor models promoted vascular maturation, reducing tumor hypoxia and increasing tumor perfusion." (PMID 37443812, 2023). "In addition, we analyzed the connection between CD93 expression and immune-related genes, immune infiltrates in the tumor microenvironment (TME), and enrichment function analysis." (PMID 36761750, 2023). "We also investigated the protein expression of CD93 in LIHC tumor tissues and adjacent tissues." (PMID 37483608, 2023). "Interestingly, Tong and colleagues found a significant increase in CD93 expression in tumor tissues compared with the adjacent normal tissues in several types of cancer." (PMID 37443812, 2023). "Moreover, CD4+ T, CD8+ T, and natural killer (NK) cells were increased in tumours treated with CD93 inhibitor." (PMID 36077754, 2022).
tumor (continued). "We found that the mRNA expression of C1QA, C1QB, C1QC, C5AR1, C3AR1, C1QR (CD93), CR1, CR2, CR3 (ITGAM), and CR4 (ITGAX) were positively associated with almost all kinds of tumor immune cells, including CD8+ T cells, CD4+ T cells, B cells, macrophages, monocytes and DCs." (PMID 34813686, 2022). "IGFBP7 is a ligand for CD93, and it is upregulated in tumour endothelial cells." (PMID 36077754, 2022). "Thus, a comprehensive assessment of the predictive value of CD93 in other cancers and the co-expression and role of CD93 on tumor and stromal cells in the TME require further elaboration." (PMID 36389798, 2022). "Ddx5 was increased in the whole skin lesions of MC903- or IMQ-treated Cd93–/– mice compared with their wild-type counterparts, along with fewer plaques on the ears or dorsal skin and reduced expression of Il4, Il13, Ccl11, Ccl17 and Ccl22 or Cxcl1, Cxcl2, Ccl20, Il23, Il17a and Il36γ." (PMID 36271146, 2022). "CD93 is a transmembrane receptor found overexpressed in tumor vessels of varied cancer types." (PMID 35978433, 2022). "CD93 is highly involved in tumor immunity and may act as a novel immune checkpoint in immunotherapy of these cancers." (PMID 36389798, 2022). "Lastly, GSEA was used to study the biological role of CD93 in different tumor tissues." (PMID 35242761, 2022). "Additionally, single-cell sequencing revealed that CD93 is predominantly co-expressed on tumor and stromal cells, such as endothelial cells, cancer-associated fibroblasts (CAFs), neutrophils, T cells, macrophages, M1 and M2 macrophages." (PMID 36389798, 2022). "CD93 is highly expressed in tumour endothelial cells in the B16 melanoma model." (PMID 36077754, 2022). "Therefore, therapeutic strategies that block CD93 in the tumor microenvironment are expected to benefit patients with malignancies." (PMID 36389798, 2022). "CD93 knockdown markedly reduced the angiogenesis and tumor growth of GBM in vivo and in vitro." (PMID 36006582, 2022). "Targeting CD93-related signaling pathways in the tumor microenvironment may be a novel therapeutic strategy for tumor immunotherapy." (PMID 36389798, 2022). "In addition, we found that the expression of CD93 was significantly correlated with the level of immune infiltration in tumor tissues." (PMID 35265666, 2021). "We found that, in COAD, BLCA, KIRC, and LIHC, the gene set of the CD93 high expression group was mainly enriched in the endothelial cell migration and tissue migration pathway, which may be closely related to tumor angiogenesis." (PMID 35265666, 2021). "Growing evidence indicated that CD93 plays an important regulatory role in tumor angiogenesis." (PMID 35265666, 2021). "Thus, our data show that fibronectin matrix is mainly deposited and organized in fibrillary structures by endothelial cells in GL261 tumors, and indicate that CD93 expression is critical for correct organization of fibronectin during tumor angiogenesis." (PMID 29763414, 2018). "Importantly, we found that a high expression of CD93 in tumor vessels correlated with shorter survival of patients with astrocytomas of WHO grades III–IV." (PMID 29763414, 2018). "Notably, a substantial reduction of fibronectin deposition was found in the CD93–/– GL261 tumor, and disrupted fibronectin fibers were observed associated with the tumor vasculature." (PMID 29763414, 2018). "Our study shows that MMRN2 is a key interaction partner of CD93 during tumor angiogenesis." (PMID 29763414, 2018). "When comparing the genotype frequencies of SNP rs2749817 to tissue levels of total CD93, the tumour tissue levels were significantly higher (20 %) among patients with T/T genotype (mean, 8.3; SD, 3.10 ng/mg) compared with C/C and C/T genotypes (mean, 6.9; SD, 3.36 ng/mg) (P = 0.037)." (PMID 26008729, 2015). "Total CD93 levels were 82 % higher (P < 0.001) in tumours compared to matched normal tissues." (PMID 26008729, 2015).
tumor (continued). "Increased CD93 expression in endothelial cells could be involved in the response to local inflammation and on-going angiogenesis within the tumour." (PMID 26008729, 2015). "Several receptor-ligand pairs were enriched, Including CLU-TREM2,CCL14-CCR1,APP-TREM2,SEMA3F-NRP2,CD93-IFNGR1 and CCL23-CCR1.The CLU-TREM2 interaction might modulate the activation state of macrophages and promote their polarization toward a tumor-associated macrophage (TAM) phenotype." (PMID 41394809, 2025). "In addition, the Cd93 and Ccl21a mRNA levels in tumor-bearing mice were inversely correlated." (PMID 38250037, 2024). "In addition to promoting CD93 expression in pMCs, the tumor also activates the CD93 pathway in pMCs because we found that C1q was responsible for CD93-mediated inhibition of CCL21 production by pMCs, and the C1q level was enhanced in both mice with lung tumors and lung tumor patients." (PMID 38250037, 2024). "Likewise, the role of CD93-IGFBP7 interaction in tumor angiogenesis seems to be important." (PMID 38468017, 2024). "Similarly to the HCmel12 model, LLC1 tumor growth was reduced in CD93–/– mice." (PMID 38441970, 2024). "Furthermore, after grouping STAD patients based on their tumor stage, we found that the gene expression of CD93 was comparable between normal tissues and stage one STAD tissues, which were significantly lower than that in STAD tissues with higher stages (range from stage two to four)." (PMID 39190192, 2024). "Interestingly, the authors found that this effect was associated with increased vascular permeability and decreased vascular perfusion of tumor cells caused by a decreased vessel functionality due to the absence of CD93." (PMID 37443812, 2023). "We showed that CD93 mainly played roles in the tumor-associated vasculature, MMRN2 mainly played roles in the quiescent vasculature, and IGFBP7 could play roles in both the quiescent and tumor-associated tumors vasculature." (PMID 37660019, 2023). "Moreover, they found that CD93 regulated β1 integrin during tumor vascularization." (PMID 37443812, 2023). "Moreover, CD93 expression was upregulated in tumor vasculature, and antibody blockade might inhibit the overexpressed CD93 in tumor vessels and normalize the CD93 signal." (PMID 37660019, 2023). "Sun and colleagues also reported that overexpression of the IGFBP7-CD93 pathway in patients who received anti-PD-1/PD-L1 treatment was related to worse treatment effect, and blocking this axis by CD93-neutralizing antibody could promote tumor therapy by regulating the TME." (PMID 37660019, 2023). "In addition, we observed that CD93 has a key role in tumor vascular maturation and extracellular matrix organization and is a potential therapeutic target, and a previous study showed that CD93 regulates Integrin β signaling activation and fibronectin fibril organization during tumor angiogenesis." (PMID 37727789, 2023). "As expected, our data showed that CD93 was highly positively associated with almost all checkpoint genes in most cancers, which significantly indicated that CD93 may play an essential role in tumor immunity and may be the next promising marker in immunotherapy." (PMID 35242761, 2022). "However, the specific mechanisms of CD93 in tumor immunity remain largely undiscovered." (PMID 36389798, 2022). "In addition, CD93 was closely related to immune cell infiltration in tumor tissues." (PMID 35265666, 2021). "However, the mechanisms through which CD93 affects sprouting angiogenesis and the architecture of tumor vessels are still largely unknown." (PMID 29763414, 2018). "The expression of three transgenes in the Engineered DCs leads to significant tumor reduction in both generations of Engineered DCs, showcasing the importance and role of the immune-modulating properties of CD40L, CD93, and CXCL13." (PMID 41295503, 2025).